TERT (telomerase reverse transcriptase)
Diseases named in the same sentence as TERT in open-access papers (continued):
Sharing a sentence is not in itself a finding about the gene and the disease.
tumor (continued). "Considering our detection rates of TERT promoter mutations in ctDNA are lower (53%) than these reports, it would be necessary for this investigation to be conducted in a larger cohort controlling for tumor burden, metastatic sites and mutation variety." (PMID 29108273, 2017). "However, tumor size was significantly larger in their study than in the present study (3.14±1.62 cm vs. 1.61±0.97 cm for TERT mutation-positive cases and 2.48±1.58 cm vs. 1.14±0.72 cm for TERT mutation-negative cases in Liu’s and our studies, respectively)." (PMID 27064992, 2016). "In addition to the relationship between small tumor size and a lower TERT promoter mutation rate, the small tumor sizes in the present study also indicate that our sample primarily included low-risk PTCs." (PMID 27064992, 2016). "Specifically, TERT promoter mutations were significantly associated with older patient age (P < 0.001), larger tumor size (P < 0.001), capsular invasion (P < 0.001), extrathyroidal invasion (P < 0.001), advanced disease stage (P = 0.003), and higher MAICS score (P < 0.001)." (PMID 26943032, 2016). "In addition, we discuss the importance of genetic alterations, such as mutations in the telomerase reverse transcriptase (TERT) promoter, for the diagnosis, prognosis, and tumor stratification for development of more effective treatment approaches." (PMID 26943571, 2016). "Of 276 HCC tumor DNA samples sequenced, 85 (31%) carried TERT promoter mutations." (PMID 27056898, 2016). "Therefore, immortal hESCs are as uninformative with regard to cancer-associated TERT mutations as immortal tumor tissue or cell lines." (PMID 26194807, 2015). "Moreover, T228C mutation in BSCS can restore the normal TERT expression and abolish its tumor initiating capacity greatly." (PMID 26143634, 2015). "Based on this tumor spectrum, TERT promoter mutations have been hypothesized to preferentially promote tumor progression in tissues with relatively low rates of self-renewal." (PMID 26194807, 2015). "It is, however, unknown whether these TERT mutations present in the tumor lead to longer white cell telomere length in these studies." (PMID 25809795, 2015). "The patient’s brain metastasis was a BRAF V600E mutated, NRAS WT, TERT C250T mutated tumor with evidence of germline SNPs that may be associated with improved OS." (PMID 26597176, 2015). "The heterogeneity between our studies was significantly reduced in the analysis of the cancer type subgroups, indicating that the effect of TERT polymorphisms may be modified by tumor origin." (PMID 26042809, 2015). "Within each tumor type, TERT promoter mutations were associated with an older age at diagnosis." (PMID 24722048, 2014). "For the PGL group, 3/12 cases (25%) expressed TERT, including the sole mutation-positive tumor." (PMID 24803525, 2014). "According to the initial classification of tumor types with TERT mutations at frequencies over 15 % (TERT-high) vs. below this threshold (TERT-low), our report suggests distinct baseline telomerase activity of the cell of origin in each of the subgroups (Group 3 ≥ Group 4 > WNT >> SHH)." (PMID 24174164, 2013). "In cancer cells, TERT has been linked to genomic instability and tumour cell proliferation." (PMID 20628624, 2010). "Increased TERT expression, being the net effect of TERT promoter mutations, leads to elevated telomerase activity, which enables cells to escape replicative senescence and promotes sustained cellular proliferation—key mechanisms implicated in tumour progression and maintenance." (PMID 40936011, 2025).
tumor (continued). "Notably, the RAS+TERT group, while showing comparable metastasis rates (55.6%, 5/9 cases), exhibited substantially larger tumor diameters (mean 56 mm), suggesting potential mechanistic differences in how these mutations influence tumor growth patterns." (PMID 40805132, 2025). "The presence of foci of infiltrative insulae of tumor cells, surrounded by a prominent desmoplastic reaction at the advancing edge of the tumors, having an age at diagnosis ≥ of 45 or 55 years old, and tumor relapse revealed a meaningful trend for an association with TERT amplification." (PMID 40272676, 2025). "The tumor lineage and aggressive potential was confirmed by extensive genetic testing revealing a high tumor mutational burden and pathogenic mutations in TERT, NRAS, and NF1, alongside alterations in PBRM1 and FAT1, which may contribute to the tumor's unique morphology." (PMID 40125165, 2025). "Therefore, the VAF of the TERT promoter mutations could in theory provide insights regarding the clonal status of this mutation in each tumor, potentially allowing comparisons between the cases." (PMID 39363120, 2024). "In addition, a recent pan-cancer analysis of 10 336 patients sequenced using MSK-IMPACT showed variability in the prevalence of TERT mutations across cancer types and found an association between the presence of TERT promoter mutations and higher tumor mutational burden (TMB) and neoantigen load." (PMID 37462445, 2024). "Furthermore, TERT gene expression may vary between different regions of the same tumor, which may lead to unreliable diagnostic results." (PMID 37830090, 2023). "Interestingly, TERT amplification could be characterized as an independent risk factor for worse overall survival in multivariate analysis in patients with pT1N0-3 tumor stage (HR = 2.440, 95% CI 1.095–5.440, p = 0.029)." (PMID 37848472, 2023). "TERT promoter mutations were seen in 8.7% (16/184) of PTMCs and were significantly associated with adverse clinico-pathological characteristics, such as older age (p = 0.0001), extrathyroidal extension (p = 0.0156), DM (p < 0.0001), stage IV tumors (p < 0.0001) and tumor recurrence (p = 0.0048)." (PMID 35360077, 2022). "Thus, we supposed that TERT promoter mutation aided in the growth of tumor." (PMID 36713542, 2022). "In addition to ETV6-NTRK3 gene fusion, TERT promoter region mutation may be another factor driving tumor progression." (PMID 36585729, 2022). "The high percentage of clinically aggressive tumours that we observed showed promoter methylation, but the absence of promoter mutations (60%, 12/20) denotes the limited prognostic predictive value of testing only TERT promoter mutations, which is in consonance with previous studies." (PMID 35979662, 2022). "Thus, the combined assessment of TERT promoter mutation and methylation status or tumor mutational burden may stratify high-risk NMIBC patients for personalized intervention." (PMID 36713366, 2022). "Additionally, we showed that TERT genetic variants could be potential prognostic biomarkers of BC associated with tumor invasiveness." (PMID 35563554, 2022). "Furthermore, a high VAF for the TERT c.-124C > T mutation correlates with tumor progression." (PMID 35713686, 2022).
tumor (continued). "Interestingly, we observed that the contralateral compensatory activation of the operculum region was mostly dependent on some molecular parameters of the tumors, such as IDH-1 mutation, TERT mutation, and deletion of 1p19q, instead of the pathological grade of the tumor." (PMID 35720068, 2022). "Although events associated with TERT upregulation are uncommon and unique in disease‐free associated tumours, these events are particularly frequent and co‐occur in clinically aggressive tumours, which suggests a positive selection of these attributes during cancer progression." (PMID 35979662, 2022). "Thus, it is presumed that the biomarker function of TERT mutations might be more apparent in early-stage HCC but was gradually outweighed by the tumor-promoting effects of other concomitant driver mutations emerging during HCC progression." (PMID 33946181, 2021). "Notably, the surrounding mucosa adjacent to tumours with -124 C>T mutated TERT promoter had the shortest telomeres (p=0.016), and, in line with our previous studies, adjacent mucosa with shorter telomeres (below the median value) showed a high, albeit not significant risk of tumour relapse." (PMID 34858860, 2021). "Furthermore, tumor tissues from HBV infected patients displayed TERT promoter mutations and TERT gene amplification, which rarely co-occurred with HBV integration in the TERT locus, while highly rearranged copy number profiles have been found in HBV-related liver tumors." (PMID 33614973, 2021). "The tumor size was larger (1.006 ± 0.829 versus 2.285 ± 1.938, p = 0.035), and extrathyroidal extension, resection margin involvement and angioinvasion were significantly higher in the TERT promoter mutation group, and the T, N, and overall stage of these patients were more advanced." (PMID 34070093, 2021). "Interestingly, we confirmed that telomeres in mucosa adjacent to TERT promoter mutated tumours were significantly shorter than those adjacent to tumours retaining unmutated TERT promoter, and additionally we found that the mucosa adjacent to -124 C>T mutated tumours had the shortest telomeres." (PMID 34858860, 2021). "Direct approaches include immunotherapy specifically targeting TERT tumor-associated antigens, such as anti-sense oligonucleotides (e.g., Imetelstat/GRN163L) and small-molecule inhibitors (e.g., BIBR1532) and small molecule inhibitors could be used to bind telomerase and inhibit telomere elongation." (PMID 34947936, 2021). "Thus, we can speculate that high TERT levels conferred by the -124 C>T TERT promoter mutation and/or rs2853669 T/T genotype may promote tumour progression, probably as a consequence of the extra-telomeric non-canonical functions of telomerase." (PMID 34858860, 2021). "Activation of telomerase reverse transcriptase (TERT), the catalytic protein subunit of telomerase, is induced by mutations in its promoter region, namely C250T and C228T, the latter being more prevalent, which promotes tumourigenesis by enabling replicative immortality in tumour cells." (PMID 34062862, 2021). "However, due to the insufficient number of patients in each subgroup, the interesting issues of whether the prognostic performance of TERT mutations may vary with tumor stage, treatment, and/or the cause of HCC should be confirmed in larger studies." (PMID 33946181, 2021). "In addition to the clinical biomarkers, univariable analysis, which introduced the WHO grade as an additional interaction term and thus excluded its effects on tumor growth, suggested that the status of MGMT, TERT, and C250T were associated with tumor growth rate." (PMID 32388499, 2020). "The lack of a strong significant association between TERT polymorphisms and circulating TERT mRNA levels may be explained by the fact that plasma TERT mRNA derives from apoptosis/necrosis of tumor cells, where several other molecular pathways can affect telomerase expression." (PMID 33113831, 2020).
tumor (continued). "Furthermore, tumor necrosis seems to be closely related to TERT promoter mutations." (PMID 32509858, 2020). "Systematic analysis of 6,835 tumor samples from 31 different human cancers revealed that TERT expression was present in 73% of all samples, which was associated with genomic alterations of TERT, such as point mutations, rearrangements, DNA amplifications and transcript fusions." (PMID 31757062, 2019). "In fact, Chiba and colleagues recently demonstrated that reactivation of telomerase via TERT promoter mutations allows for melanomagenesis first by protecting the shortest telomeres rather than by elongating the telomeres, and subsequently by sustaining tumor cell proliferation." (PMID 29695835, 2018). "Although is it evident that TERT promoter mutation status and telomere regulation is variable and complex among different cancers types, particularly due to the variety related to tumor cell origin, tumor subtype, our proposed model is further substantiated by others studies." (PMID 29463038, 2018). "Interestingly, TERT promoter mutation at C250T was identified in patient TT10902 in both tumor and cell line, which may help understand the telomerase function in DIPG." (PMID 29100338, 2017). "While it is unclear whether the BRAF or TERT mutations in this patient’s tumor had an impact on his early brain-only recurrence or his eventual prolonged survival, ongoing investigation is needed to understand the implications of MBM somatic mutational profiles." (PMID 26597176, 2015). "Thus, this suggests that the TERT mutations and increased telomerase activity may maintain a tumor phenotype by stimulating an inflammatory response and angiogenesis as suggested by the increased IL-6 levels." (PMID 26143636, 2015). "Next, we assessed the impact of the aberrant telomerase activity of TERT promoter-mutation-containing cells by directly comparing the telomerase levels in fibroblasts and NPCs that carried the promoter mutations to the telomerase activity found in three established tumor cell lines." (PMID 26194807, 2015). "Such mutations may indicate an increased TERT activity and immortalization of the tumor cells." (PMID 25093008, 2014). "In line with this hypothesis, a recent study by Killela and colleagues identified recurrent mutations in the C228T or C250T positions of TERT promoters in ODGs with 1p19q deletions and suggested that these mutations may promote a self-renewal capability in these tumours." (PMID 25277207, 2014). "Therefore, we hypothesized that this functional polymorphism in the downstream of TERT gene might contribute to the tumor susceptibility." (PMID 21929825, 2011). "These analyses identified several differentially methylated genes linked to invasiveness (e.g., PHYHD1, WNT4, STAT6, CDH1, CDH13), aggressive behaviour (e.g., AIP, PDCD1, LINE-1), and tumour regrowth (e.g., TERT, FAM90A1, ING2)." (PMID 41866138, 2026). "The positive association between TERT and LC3 suggests the presence of additional metabolic adaptation mechanisms supporting tumor survival." (PMID 42113085, 2026). "Molecular profiling identified NRAS Q61R and TERT promoter mutations, equivocal MYC amplification, and an elevated tumor mutational burden." (PMID 42158418, 2026). "Among the shelterin components, TPP1 showed the strongest correlation with TERT, and its expression increased with tumor multiplicity and advancing stage." (PMID 41751263, 2026). "High-risk clinicopathological features, such as tumor size >2 cm, extrathyroidal extension, and aggressive histological variants, are discussed alongside molecular markers (BRAF V600E, TERT, RET/PTC) that predict metastatic potential." (PMID 41684449, 2026).
tumor (continued). "Telomere length-sensitive telomerase reverse transcriptase (TERT) regulation in in vivo tumour xenografts (A) Scheme depicting the generation of tumour xenograft with HT1080-ST or HT1080-LT cells." (PMID 41026782, 2025). "The enrichment for this subpopulation was additionallyassociated with a detection improvement of a relevant tumor-derivedmutation in the TERT gene promoter." (PMID 40056466, 2025). "TERT activation also confers a selective advantage to tumor cells by promoting proliferation, migration, and invasiveness, key elements of metastasis." (PMID 41155227, 2025). "Accordingly, inhibiting TERT or its upstream tumor-specific transcription factor GA-binding protein transcription factor subunit beta 1 (GABPB1) was shown to inhibit tumor growth." (PMID 40463649, 2025). "Including molecular biomarkers beyond MGMT, like IDH1/2 mutation status, ATRX loss, TERT promoter mutation, EGFR amplification, and 1p/19q co-deletion, can improve the model’s understanding of tumor biology." (PMID 41584616, 2025). "Following harvesting, tumours were first characterized: TL was overall higher in all LT tumours compared to HT1080-ST tumours; increased TERT and telomerase activity was retained in HT1080-LT tumours relative to ST." (PMID 41026782, 2025). "The TERT promoter and ATM mutations further contribute to the aggressive cytologic features of the tumor." (PMID 40125165, 2025). "Immunohistochemistry (IHC) staining further confirmed the inhibitory effects of TERT knockdown on tumor proliferation." (PMID 40688111, 2025). "This architecture supports dual-task decoders, enabling concurrent voxel-wise tumor delineation and subject-level classification of key genomic markers, including the IDH gene mutation, the 1p/19q co-deletion, and the TERT gene promoter mutation." (PMID 41007223, 2025). "At the systemic level, circulating tumor cells (CTCs) were detected in peripheral blood to assess tumor burden, and the proportion of TERT + leukocytes was analyzed to reflect systemic immune status." (PMID 41417416, 2025). "TRF2-ChIP from tumour tissue showed HT1080-ST had significantly more TRF2 occupancy at the TERT promoter than HT1080-LT, consistent with results from cultured cells." (PMID 41026782, 2025). "The mechanism of TERT activation evolved with tumor cell dedifferentiation in 67% of the PDCs and 100% of the ATCs." (PMID 40272676, 2025). "Using a multi-sample phasing in the analysis of somatic CNV across 22 tumor types showed that focal TERT amplifications were frequently subclonal." (PMID 40272676, 2025). "In vivo experiments demonstrated that TERT knockdown significantly inhibited tumor growth and reduced cell proliferation in both 143b and U2OS OS xenograft models." (PMID 40688111, 2025). "The enrichment of the TERT variant in the stromal component after macrodissection is particularly notable given TERT’s established role in tumour biology." (PMID 40936011, 2025). "In the realm of energy metabolism, TERT supports tumor growth by modulating glucose and fatty acid metabolic pathways." (PMID 39871386, 2025). "Beyond promoting cellular proliferation, TERT also plays a crucial role in modulating the tumor microenvironment." (PMID 40243493, 2025).